OR6M1 (olfactory receptor family 6 subfamily M member 1)
Description:
Odorant receptor.
Synonyms: OR11-271
Tractability: Antibody: UniProt places it where antibodies can reach, with medium confidence; UniProt predicts a signal peptide or a membrane-spanning region; its Gene Ontology location is reachable by antibodies, with medium confidence.
Gene: Protein-coding gene on chromosome 11 (123,805,408 to 123,806,349, reverse strand). Ensembl gene ENSG00000196099.
Subcellular location: Cell membrane
Pathways (Reactome):
Sensory Perception: Expression and translocation of olfactory receptors
Gene Ontology:
Molecular function: olfactory receptor activity; G protein-coupled receptor activity
Biological process: detection of chemical stimulus involved in sensory perception of smell; G protein-coupled receptor signaling pathway
Cellular component: plasma membrane; membrane
Genetic constraint (gnomAD): Loss-of-function variants: 0 observed, 0.0866 expected, observed/expected ratio (o/e) 0, 90% interval 0 to 1.89. That is too few expected variants to judge how well the gene tolerates losing a copy. Missense variants: 357 observed, 387.72 expected, observed/expected ratio (o/e) 0.92, 90% interval 0.84 to 1. Synonymous variants: 165 observed, 152.36 expected, observed/expected ratio (o/e) 1.08, 90% interval 0.95 to 1.23.
Homologues: Orthologues: chimpanzee OR6M1 (99% identical), macaque OR6M1 (94% identical), dog OR6M1 (88% identical), pig OR6M1 (83% identical), guinea pig OR6M1 (78% identical). Paralogues in human: OR6J1 (55% identical), OR6S1 (51% identical), OR6T1 (50% identical), OR6F1 (50% identical), OR6C4 (47% identical), OR6X1 (47% identical), OR6C74 (46% identical), OR6C1 (45% identical), OR6C3 (45% identical), OR6C75 (45% identical), OR6C76 (44% identical), OR6C70 (44% identical), and 6 more.
Diseases named in the same sentence as OR6M1 in open-access papers:
OR6M1 is named in the same sentence as 1 disease in open-access papers, as found by Europe PMC text mining. Sharing a sentence is not in itself a finding about the gene and the disease. The quoted sentences say what the papers report.
breast carcinoma (1 paper, 2021). "In this study, we presented an optimized strategy that shows the potential of orphan OR6M1 as a new drug target in the MCF-7 breast cancer cell line by integrating SPR-based ligand screening and cell-based assays." (PMID 34065710, 2021). "Herein, we present an experimental strategy using a surface plasmon resonance (SPR) system and a cell-based assay that allowed the identification of orphan OR6M1 as a new anticancer target in the MCF-7 breast cancer cell line." (PMID 34065710, 2021).